MIRLET7F2 (microRNA let-7f-2)
Synonyms: hsa-let-7f-2; LET7F2; MIRNLET7F2; let-7f-2
Gene: MicroRNA gene on chromosome X (53,557,192 to 53,557,274, reverse strand). Ensembl gene ENSG00000208012.
Gene Ontology:
Biological process: miRNA-mediated post-transcriptional gene silencing
Cellular component: RISC complex
Homologues: Orthologues: chimpanzee ptr-let-7f-2 (100% identical), dog MIRLET7F2 (100% identical), guinea pig MIRLET7F2 (100% identical), macaque mml-let-7f-2 (100% identical), mouse Mirlet7f-2 (100% identical), pig ssc-let-7f-1 (100% identical), rabbit MIRLET7F2 (100% identical), rat Mirlet7f2 (100% identical), tropical clawed frog xtr-let-7f (89% identical), zebrafish mirlet7g-2 (83% identical), zebrafish mirlet7g-1 (78% identical). Paralogues in human: MIRLET7A1 (87% identical), MIRLET7A3 (72% identical), MIRLET7F1 (72% identical), MIRLET7D (70% identical), MIRLET7G (70% identical), MIRLET7C (65% identical), MIR98 (64% identical), MIRLET7E (64% identical), MIRLET7A2 (61% identical), MIRLET7I (59% identical).